IL1B (interleukin 1 beta)
Diseases named in the same sentence as IL1B in open-access papers (continued):
Sharing a sentence is not in itself a finding about the gene and the disease.
breast cancer (continued). "To establish the effect of BRCA1 on inflammasome activation in mammary cells, we analyzed IL‐1β secretion and caspase 1 activation in MCF10A cells with detectable inflammasome‐associated components, compared to several breast cancer cell lines." (PMID 32195105, 2020). "The IL-1β response driven by breast cancer prevented the differentiation of metastasis-initiating cancer cells (MICs) into highly proliferative E-cadherin-positive progeny." (PMID 31492049, 2019). "In conclusion, this study substantiates the rationale for a therapeutic design that simultaneously targets multiple cytokines, such as OSM, IL-6, and IL-1β, as these cytokines are strongly correlated with each other in breast cancer." (PMID 31007849, 2019). "Immunohistochemistry for S100A4, Fibronectin, RAS, IL-1B, IL-1R1 and γ Catenin was performed on mammary tumours and metastases in human bone implants." (PMID 31783893, 2019). "Others have shown that reduced mammary stroma IL-1β production and increased mammary tumor IL-1Ra levels play roles in ENL’s anti-angiogenic effects, suggesting that ENL has additional anti-inflammatory effects that contribute to its anti-tumor activity." (PMID 30367332, 2019). "IL-1β enhanced the invasion of breast cancer cells via upregulating MMP-9 by activating focal adhesion kinase (FAK) and proto-oncogene tyrosine-protein kinase Src." (PMID 31492049, 2019). "IL-1β induces IL-6 production in breast cancer cells, as well as additional cytokines and growth factors including TGF-β, TNF-α, and EGF." (PMID 31231372, 2019). "Macrophage-derived IL-1β enhanced the migration of breast cancer cells and their adhesion to lymphatic endothelial cells." (PMID 31492049, 2019). "Collectively, these results suggest that OSM, IL-6, and IL-1β are interrelated in breast cancer patient metastasis and survival." (PMID 31007849, 2019). "Expression of IL-1α, IL-1β, and their receptors in human breast cancer tissues results in the activation of a population of cells and subsequently contributes to angiogenesis, tumor proliferation, and tumor invasion in the microenvironment." (PMID 31182982, 2019). "Firstly, IL1β activates inflammatory NF-κB signaling pathway in the tumor cells to promote the development of breast cancer." (PMID 31398937, 2019). "Interesting interactions between primary tumors and distant metastatic sites in breast cancer, involving IL-1β, have also recently been elegantly described." (PMID 31231372, 2019). "Here, by using the TCGA breast cancer dataset we found that TNFα and IL-1β were expressed in significantly higher levels in basal tumors than in luminal-A tumors (Figures 1A1,B1)." (PMID 31031757, 2019). "The data are in line with our previously published research in which we identified IL-1B as being upregulated in mammary tumours that metastasised to human bone compared with mammary tumours that did not metastasise." (PMID 31783893, 2019). "Next, we examined if PDGFB and IL1β expression are predictive of primary ER+ breast cancer prognosis using SurvExpress online database." (PMID 31419632, 2019). "Upregulation of BIRC3 induced by IL-1β results in chemoresistance to doxorubicin in breast cancer cells." (PMID 30630498, 2019). "IL-1β was able to enhance tamoxifen resistance in breast cancer cells by downregulating the estrogen receptor α (ERα)." (PMID 31492049, 2019). "Similar to our published studies, which showed that OSM is important for osteolytic breast cancer metastasis to bone, IL-1β also stimulates the development of bone metastases." (PMID 31007849, 2019).
breast cancer (continued). "To reduce the probability of saturating the cell’s capacity to produce IL-6 and to better assess a possible synergistic interaction between OSM and IL-1β in breast cancer cells, we decreased the amount of OSM used in the experiments from 25 ng/mL to 10 ng/mL." (PMID 31007849, 2019). "It has recently been shown that administration of inhibitory antibodies targeting IL-1β results in the augmentation of anti-tumor cell immunity in a murine model of breast cancer." (PMID 31231372, 2019). "Pharmacological or genetic inhibition of IL-1β reduces tumor growth and metastasis in murine and human breast cancer models." (PMID 31552036, 2019). "Using the Curtis TCGATM dataset, we have determined that there is a correlation between expression levels of OSM, IL-6, and IL-1β and reduced breast cancer patient survival (r = 0.6, p = 2.2 x 10−23)." (PMID 31007849, 2019). "Activation of IL-1β/IL–1RI/β-catenin signaling pathway was shown to activate EMT in a breast cancer cell model through the formation of a TCF/Lef/β-catenin complex leading to the sequential induction of c-Myc, CCDN1, Snail1, MMP2, and BIRC3 (cIAP2) expression." (PMID 31557902, 2019). "Cytokines such as interleukin-6 (IL-6), oncostatin M (OSM), and interleukin-1 beta (IL-1β) promote the development of both acute and chronic inflammation while promoting in vitro metrics of breast cancer metastasis." (PMID 31007849, 2019). "IL-1β involvement in breast cancer bone metastases was highlighted by its high expression in metastatic breast cancer cell lines, in serum from mice-bearing bone metastatic tumors and also in tissue samples from patients with breast cancer bone metastases." (PMID 31847214, 2019). "Higher concentrations of many inflammatory markers, including CRP, IL-1β, IL-6, and TNF-a, have been linked with a higher risk of breast cancer through the stimulation of angiogenesis, proliferation, migration, metastasis, and prevention of apoptosis." (PMID 31430979, 2019). "In this study, we investigate the effect of OSM, IL-6, and IL-1β on breast cancer patient survival as well as how these cytokines are interrelated in terms of cell signaling." (PMID 31007849, 2019). "Conversely, others reported that NLRP3 inflammasome activation and the consequent release of IL-1β and IL-18 promoted tumor growth, proliferation, invasion, and metastasis in lung cancer, melanoma, breast cancer, and head and neck squamous cell carcinoma." (PMID 31200447, 2019). "An autocrine IL-1β signaling loop has also been described for CD133+ CSCs mediating NF-κB signaling, EMT, and invasion in pancreatic cancer cell lines, and exposure to IL-1β induced motility and invasiveness in a non-invasive breast cancer cell line." (PMID 31554173, 2019). "Our previous RNA-seq analysis of IL-1β-stimulated 6D breast cancer cells showed increased expression of TP63, a gene classified in the group of drug-resistance-related genes." (PMID 30641908, 2019). "To test this, we inhibited IL1β by neutralising antibody in a bone marrow sample, prior to treating breast cancer cells in culture with conditioned media from this bone marrow and assessing CSC colony formation." (PMID 31676788, 2019). "IL-1β generated in a tissue with a tumor microenvironment dominated by TAMs promotes tumor growth and metastasis in breast cancer." (PMID 31182982, 2019). "This indicates one mechanism by which an increase in bone marrow IL1β has the potential to promote metastatic colonisation in breast cancer patients, but is a point for further investigation." (PMID 31676788, 2019). "IL1B and TNFA expression in breast cancer tissues are thus likely caused by the stromal cells present in breast cancer tissue samples." (PMID 31533776, 2019). "IL1β treatment significantly increased Wnt signalling in a 293T cell Wnt-reporter model (p < 0.0001), and Lef1 Wnt target gene expression in breast cancer cell lines (MCF7; p < 0.0001, MDA-MB-231_BH; p = 0.0083)." (PMID 31676788, 2019).
breast cancer (continued). "IL-1β conferred doxorubicin resistance to breast cancer cells by elevating the expression of the baculoviral inhibitor of apoptosis repeat-containing 3 (BIRC3), known as an EMT marker." (PMID 31492049, 2019). "We have demonstrated that OSM and IL-1β act synergistically in the production of IL-6 by breast cancer cells and in the potential exacerbation of inflammatory conditions." (PMID 31007849, 2019). "From a clinical perspective, we found that in TCGA data retrieved from the Human Protein Atlas database, breast cancer patients with elevated expression of IL-1β had better prognosis reflected in the OS." (PMID 31093512, 2019). "These analyses indicated that IL-1β is significantly upregulated in CAFs in human breast carcinomas, in correlation with disease progression." (PMID 31558756, 2019). "We demonstrated here that breast cancer cells can present caspase-1 activation, and once activated, caspase-1 can process pro-IL-1β and induce its secretion." (PMID 29386662, 2018). "The results of the association between IL-1B, IL1R1 polymorphisms and breast cancer risk have significant." (PMID 29719585, 2018). "Our data showed that DHA can activate inflammasome and induce IL-1β maturation and secretion in breast cancer cells." (PMID 29386662, 2018). "TAM provide an inflammatory microenvironment via inflammasome activation and IL-1β production which promotes, for example, breast cancer progression." (PMID 30042333, 2018). "Levels of ANGPTL4 are correlated with inflammatory markers including C-reactive protein and IL-1β in serum from patients with type 2 diabetes and breast cancer." (PMID 29563332, 2018). "The outcome of Notch-mediated positive regulation of CCL2 in breast cancer cells in synergy with IL-1β has already been described." (PMID 30154786, 2018). "Previous studies have shown that paclitaxel is capable of increasing the expression of IL-1β in primary human monocytes, T lymphocytes, human breast cancer cell lines, and macrophages." (PMID 29681766, 2018). "NKILA was reported to be upregulated by more than 12-fold by TNF-α- and IL-1β-induced NF-κB activation in breast cancer." (PMID 29379981, 2018). "IL-1B has been identified as biomarker that can be used to predict which breast cancer patients are likely to experience relapse in bone." (PMID 29760166, 2018). "Considering that IL-1B is a prognostic marker for breast cancer disease progression, it is puzzling to define a pro- or anti-tumour function for the energy-carrying molecule." (PMID 29760166, 2018). "In vitro studies have suggested so far that IL-1B correlates with increased aggressiveness of breast cancer cell lines." (PMID 29760166, 2018). "Three single nucleotide polymorphisms (SNPs) identified in IL1B, IL1R1 gene are thought to influence breast cancer risk." (PMID 29719585, 2018). "Co-culture of IL-1B-secreting macrophages and breast cancer cells results in enhanced OPG secreted by tumour cells." (PMID 29760166, 2018). "Metastatic breast cancer lines secrete IL-1β with the possible existence of other factors, which act on mesenchymal stem cells (MSCs)." (PMID 30648081, 2018). "IL-1B has been shown to have profound effects on tumour growth and metastasis in tumour types other than breast cancer, including melanoma." (PMID 29760166, 2018). "These authors found a strong association between Notch activation, IL1β and CCL2 production, macrophages infiltration in basal-like breast cancer." (PMID 29915603, 2018). "In this regard, IL-1β has been shown to induce epithelial to mesenchymal transition in breast cancer cells and IL-1 signaling has been related to inflammation and aggressiveness due to the modulation of antitumor immunity in the same type of cancer." (PMID 30622432, 2018). "In another mouse breast cancer model, the effects of interleukin (IL)-1β on the IL-17 expression of gamma delta (γδ) T cells were shown, affecting neutrophils and suppression of CD8 + T cells, also leading to the formation of metastases." (PMID 29350274, 2018).
breast cancer (continued). "By contrast, in the same model of skin carcinogenesis, ASC plays as a tumor promoter in myeloid cells, and IL-1β and inflammasome are crucial for mesothelioma development and murine mammary carcinoma progression mediated by myeloid recruitment." (PMID 30154786, 2018). "The heterotypic cell-cell interaction within the breast cancer microenvironment upregulated IL-1β/LCN2 expressions in breast cancer cells, which in turn markedly enhanced breast cancer tumour progression." (PMID 28281525, 2017). "IL1B treatment resulted in increased phosphorylation as compared to untreated controls in all five breast cancer cell lines tested for p38, and in four out of five cell lines tested for p42/44." (PMID 28143606, 2017). "In this study, we investigated OPG in the context of its role in breast cancer and inflammation, with a particular focus on IL1B." (PMID 28143606, 2017). "It has been shown that treatment with the inflammatory cytokine IL1B promotes the invasiveness of breast cancer cells in vitro." (PMID 28143606, 2017). "In summary, we have identified OPG as a potential downstream effector in the metastasis-promoting effects of IL1B in breast cancer." (PMID 28143606, 2017). "MSCs activated by IL-1β secrete other inflammatory cytokines, such as CXCL1, which is implicated through signaling through CXCR2 expressed on breast cancer cells in the dissemination, poor patient prognosis, chemo-resistance, and metastasis." (PMID 29262555, 2017). "Patients who received sevoflurane/opioid anesthesia also exhibited increased levels of protumorigenic factors, such as IL-1β and matrix metalloproteinases, compared with patients who received propofol/paravertebral anesthesia for breast cancer surgery." (PMID 28905322, 2017). "Previous study found that the expression of NKILA was regulated by TNF-α or IL1β induced NF-κB activation in breast cancer cells." (PMID 28412955, 2017). "IL1B has been shown to up-regulate Osteoprotegerin (OPG) expression in the breast cancer cell lines MCF-7 and MDA-MB-231." (PMID 28143606, 2017). "Our recent study has demonstrated that inflammasome and IL-1β play a critical role in promoting tumor growth and metastasis in breast cancer." (PMID 28955343, 2017). "Taken together, our findings suggest OPG is a downstream effector of IL1B-mediated invasion in breast cancer cells." (PMID 28143606, 2017). "Our findings supported by human data show that breast cancer patients with high-levels of IL-1β, CXCL1, CCL2, S100A8, VEGF, and IL-8 would show worse clinical outcomes." (PMID 29262555, 2017). "IL1B from macrophages or from breast cancer cells themselves can induce OPG secretion in a p38- and p42/44-dependent manner that contributes to increased invasion." (PMID 28143606, 2017). "Adding IL-1β antibody further reduced the colony number of LCN2-depleted MDA-MB-231 breast cancer cells co-cultured with MGDAs, suggesting that both IL-1β and LCN2 contribute to MGDAs-mediated tumour malignancy." (PMID 28281525, 2017). "The elevated level of IL-1β has been shown to upregulate osteoprotegerin (OPG) expression in the breast cancer cell lines MCF-7 and MDA-MB-231 by activation of p38 and p42/44 MAPK signaling pathway." (PMID 28927416, 2017). "Our results suggest that inflammasome activation and IL-1β production in TAMs provides an inflammatory microenvironment promoting breast cancer progression." (PMID 28955343, 2017). "Results demonstrate that macrophage production of IL-1β plays an important role in the migration of breast cancer cells and their adhesion to, and transmigration across, blood and lymphatic endothelial cells." (PMID 28551814, 2017). "In an analysis of publicly available human breast cancer genome-wide mRNA expression datasets from patient samples we showed that OPG mRNA expression was significantly correlated with IL1B mRNA expression." (PMID 28143606, 2017). "The results above clearly show a role for IL1B in increasing OPG secretion in breast cancer cell lines in vitro." (PMID 28143606, 2017).
breast cancer (continued). "Enhanced cell motility and invasion have also been coupled with overexpression of IL-1β within breast cancer via the upregulation of matrix metalloproteinase- (MMP-) 9, integrin-1, and E-selectin." (PMID 28607534, 2017). "IL-1β, a mediator of pro-inflammatory response is also produced by metastatic breast cancer cells (MDA-MB-231 and MDA-MB-436)." (PMID 28609459, 2017). "Given our data demonstrating that OPG is subject to regulation by IL1B-p38 and -p42/44 signaling, we sought to investigate OPG function in IL1B-mediated breast cancer invasion." (PMID 28143606, 2017). "We found that OPG mRNA expression significantly, positively correlated with IL1B mRNA expression in 11 out of 13 datasets, in agreement with what we observed for OPG and IL1B secretion in the breast cancer cell lines in vitro." (PMID 28143606, 2017). "We evaluated the association between the expression of IL-1β plus CXCL1 plus CCL2 plus S100A8 plus VEGF plus IL8 and outcomes in several cohorts of breast cancer patients." (PMID 29262555, 2017). "Basal levels of OPG and IL1B protein were examined across cell lines representing multiple breast cancer subtypes." (PMID 28143606, 2017). "Although depletion of both IL-1β and LCN2 abolished the MDGAs-mediated colony promotion of MDA-MB-231 breast cancer cells, it also caused severe inhibition of cell growth." (PMID 28281525, 2017). "Studies have indicated that the up-regulation of IL1β expression is involved in breast cancer, colon cancer, melanoma and lung cancer and promotes cell apoptosis." (PMID 28700704, 2017). "The correlation between MCT2 expression and poor prognosis in breast cancer was further strengthened when combined with either high expression of IL-1β or LCN2 (cut-off value of −ΔCt: −7.34 for IL-1β and −7.42 for LCN2, respectively)." (PMID 28281525, 2017). "IL-1β significantly augmented the adhesion and transmigration of breast cancer cell lines MCF7 and MDA-MB-231 across endothelial cell barriers." (PMID 28551814, 2017). "In human breast carcinoma tissues, IL1B levels were found elevated in higher grade tumors and in invasive breast carcinoma versus ductal carcinoma in situ (DCIS) and benign lesions." (PMID 28143606, 2017). "Given that MMP9 is regulated by TGF-β and pro-inflammatory TNF/IL-1β cytokines, expression of these cytokines was also examined in human breast carcinomas." (PMID 28423685, 2017). "It has revealed that treatment with IL1B can promote the invasiveness of breast cancer (BC) cells in vitro." (PMID 29069743, 2017). "Of all inflammatory markers investigated, we found that ox-LDL, IL-1β, and TNF-α were significantly associated with breast cancer (model I) when adjusting for matching factors." (PMID 27391324, 2016). "TG2 overexpression in MCF7 cells increased the surface expression of breast cancer stem cell marker CD44, and IL-1β stimulation of MCF7_TG2 breast cancer cells further increased CD44 expression." (PMID 27609180, 2016). "In this nested case-control study, we analyzed several biomarkers of inflammation that is ox-LDL, IL-1β, IL-6, TNF-α, WBC, neutrophils, and lymphocytes, and found significant associations between ox-LDL, IL-1β, and TNF-α and post-menopausal breast cancer." (PMID 27391324, 2016). "IL-1β treatment induced IL-6 production in TG2-overexpressing breast cancer cells and resulted in an aggressive phenotype that showed increased invasion, EMT phenotypes, and cancer stem-cell-like properties." (PMID 27609180, 2016). "Concomitant expressions of RANTES and IL-1β have also been observed in breast cancer relapsing patients." (PMID 27376091, 2016). "Treatment with TGF-β, EGF, and TNF-α after IL-1β further increased IL-6 expression in MCF7_TG2 breast cancer cells." (PMID 27609180, 2016). "Increased invasion of MCF7_TG2 breast cancer cells by IL-1β was attenuated by blocking IL-6 through anti-IL-6 antibody treatment." (PMID 27609180, 2016).